CTNS (cystinosin, lysosomal cystine transporter)
Diseases named in the same sentence as CTNS in open-access papers (continued):
Sharing a sentence is not in itself a finding about the gene and the disease.
Stroke (1 paper, 2019). Sudden impairment of blood flow to a part of the brain due to occlusion or rupture of an artery to the brain. "After introduction of the sensitive myocardial necrosis markers, the associationbetween cTns and stroke was demonstrated extensively." (PMID 30843948, 2019). "Thus, in patients with stroke and elevated cTns, an initial assessment of whetheran acute increase in the biomarker has occurred or whether it is elevated butstable is reasonable." (PMID 30843948, 2019).
metabolic disease (5 papers, 2019 to 2024). A congenital disorder (due to inherited enzyme abnormality) or acquired (due to failure of a metabolically important organ) disorder resulting from an abnormal metabolic process. "Nephropathic cystinosis (NC) is an inherited metabolic disease secondary to mutations in the CTNS gene, which encodes for cystinosin, a cystine proton symporter allowing efflux of cystine from lysosomes." (PMID 34943802, 2021). "Nephropathic cystinosis (NC) is a rare metabolic disease caused by mutations in the CTNS gene that encodes for cystinosin, the cystine carrier in lysosomes." (PMID 30669391, 2019).
kidney disease (4 papers, 2021 to 2025). "Nephropathic cystinosis is a severe monogenic kidney disorder caused by mutations in CTNS, encoding the lysosomal transporter cystinosin, resulting in lysosomal cystine accumulation." (PMID 34165243, 2021). "The possibility to monitor progressive PT dysfunction and cystine storage over time allowed us to test whether mTORC1 activation may drive the onset and progression of kidney disease in CTNS deficient mice." (PMID 37452023, 2023).
cardiovascular diseases (3 papers, 2022 to 2024). "There is a need for further clinical studies validating the circadian rhythms of cTns and their effect on the diagnostics of cardiovascular diseases, including MI, and for fundamental research clarifying the molecular mechanisms of the formation of circadian rhythms of cTns." (PMID 35336802, 2022). "Conventional biomarkers like cardiac troponin (cTns) and creatinine kinase MB (CKMB) are adopted as the golden standard in AMI diagnosis, yet the inherent limitations that other cardiovascular diseases may present exaggeration of cTns and CKMB level still exist." (PMID 35246050, 2022). "Thus, they may increase the serum levels of cTns in patients with no signs of cardiovascular diseases." (PMID 35336802, 2022).
genetic diseases (2 papers, 2019 to 2024). "At least six other CTNS nonsense mutations have been reported and it is likely that the efficacy of ELX-02 varies somewhat, depending on the specific mutation and its nearby sequence context as in other genetic diseases." (PMID 31800572, 2019).
myopathies (2 papers, 2023 to 2025). "For the first time, we identified that CTNS loss in myotubes leads to a depletion of an 18‐protein network involved in myofibril assembly and implicated in other myopathies." (PMID 41208577, 2025).
cancer (1 paper, 2025). A tumor composed of atypical neoplastic, often pleomorphic cells that invade other tissues. "Background and Objectives: Cardiac injury caused by cancer therapy can be detected early using high-sensitivity cardiac troponins (hs-cTns), and this is crucial for preventing irreversible consequences." (PMID 41303748, 2025). "Although increasing evidence suggests that hs-cTns in cancer populations can predict all-cause mortality and left ventricular ejection fraction (LVEF) decline, little is known about the prediction of other systolic and diastolic functional echocardiographic parameters." (PMID 41303748, 2025).
CTNS also shares sentences with these, for which no sentence is quoted: Cachexia (2 papers); cardiomyopathies (2); tumor (2); acute myocardial infarction (1); Alzheimer disease (1); atrial fibrillation (1); bone disorder (1); cardiac arrhythmia (1); corneal disease (1); depression (1); end-stage renal disease (1); heart failure (1); hyperparathyroidism (1); hypersplenism (1); Hypokalemia (1); hypophosphatemic rickets (1); ischemic heart disease (1); kidney (1); left ventricular hypertrophy (1); Lysosomal disease (1); Nephropathy (1); ocular cystinosis (1); Patent foramen ovale (1); Polyuria (1); pulmonary arterial hypertension (1); Renal failure (1); renal tubular acidosis (1); Right ventricular dilatation (1); Splenomegaly (1); thyroiditis (1).
A further 1 disease shares a sentence with CTNS in 1 paper.